KLK8 (kallikrein related peptidase 8)
Diseases named in the same sentence as KLK8 in open-access papers (continued):
Sharing a sentence is not in itself a finding about the gene and the disease.
depression (continued). "In conclusion, we have performed EWAS of depression symptomatology score in a unique cohort of elderly monozygotic twins and identified blood methylation levels at KLK8, DAZAP2, MAD1L1, SLC29A2, AKT1, and other genes, as well as several DMRs across the genome to be associated with this trait." (PMID 31477683, 2019). "In this study we performed an EWAS of depression symptomatology in a large cohort of monozygotic twins with two different statistical approaches and we identified DNA methylation levels in KLK8 and DAZAP2 genes to be most associated with the depression symptomatology score." (PMID 31477683, 2019). "Finally, we demonstrated that running exercise reversed KLK8 upregulation and inactivated Met/Src/Btk/NF-κB signaling pathways, thereby attenuating neuroinflammation, improving neuroplasticity, and alleviating depression-like behaviors in STZ-induced diabetic mice." (PMID 40521191, 2025). "This was supported by additional analyses of our findings in four independent methylomic cohorts, where DNAm variation at 7 CpG sites located in the KLK8 promoter region was associated with depression symptomatology in the GSMS cohort, but not in the other cohorts." (PMID 34715912, 2021). "However, investigation of the link between KLK8 promoter DNAm levels and depression-related phenotypes collected from four methylomic cohorts identified significant association (p value < 0.05) between severity of depression symptomatology and blood DNAm levels at seven CpG sites." (PMID 34715912, 2021). "Our present data raised the possibility of KLK8 as a potential therapeutic target for depression and provided a new mechanism for CUMS-induced depression." (PMID 37076499, 2023). "The test was performed for two CpG sites, the candidate locus from depression symptomatology EWAS (CpG2) and its neighboring site (CpG1) located in KLK8 promoter region." (PMID 34715912, 2021). "Assessment of KLK8 mRNA levels in peripheral blood from 186 patients diagnosed with major recurrent depression (MRD) compared to 105 healthy subjects, revealed significantly higher KLK8 expression in patients." (PMID 32414324, 2020). "Our recent research revealed that KLK8 mediated the proteolytic processing of the NCAM1 extracellular domain, thereby exerting a pro-apoptotic effect on hippocampal neurons during the pathogenesis of chronic unpredictable mild stress (CUMS)-induced depression." (PMID 40521191, 2025). "When excluding participants with elevated depression (CES-D≥18) form our analyses, our results on the association of KLK8 and aMCI did not change." (PMID 34930454, 2021). "Furthermore, it was shown that KLK8 mRNA is significantly more abundant in blood samples from patients affected by MRD, compared to patients suffering from first episode depression." (PMID 32414324, 2020). "Other studies that investigated DNA methylation signatures of depression in discordant monozygotic twins study design implicated epigenetic changes in VDR26, HOXB7, CACNA1C, STK32C, NR1C3, and MYC genes among others, but not in KLK8 or DAZAP247,108,117,118." (PMID 31477683, 2019). "The present study additionally contributed to the understanding of this complex system, demonstrating that KLK8 mediated the ectodomain shedding of NCAM1, which may represent a potent mechanism for neuronal apoptosis in the hippocampus during the pathogenesis of CUMS-induced depression." (PMID 37076499, 2023).
lung carcinoma (8 papers, 2012 to 2025). "Controversial views exist about the roles of KLK8 in lung malignancies and little is known about the associations between KLK8 and lung cancer immunity." (PMID 38273291, 2024). "KLK8 (human kallikrein 8) impedes lung cancer cell invasiveness by degrading fibronectin, reducing integrin signaling, and inhibiting actin polymerization, thus slowing cancer cell motility." (PMID 40124684, 2025). "Abnormal KLK8 expression has been found in several malignancies, including ovarian, cervical, gland and lung cancers." (PMID 34395235, 2021). "Collectively, the functions of KLK8 are context-dependent, especially in lung cancer." (PMID 38273291, 2024). "Previous studies have found that abnormal expression of KLK8 was associated with several malignancies, including ovarian, cervical, gland and lung cancers.However, the expression level and prognostic significance of KLK8 in PDAC are still unknown." (PMID 34395235, 2021).
Alzheimer disease (7 papers, 2018 to 2025). A progressive, neurodegenerative disease characterized by loss of function and death of nerve cells in several areas of the brain leading to loss of cognitive function such as memory and language. "In fact, increased levels of KLK8 have been implicated in the pathogenesis of various diseases including psoriasis 54, schizophrenia, mood and anxiety disorders 15,55, Alzheimer's disease 56,57 and several types of cancers 58-60." (PMID 33754057, 2021). "In fact, increased levels of KLK8 have been implicated in the pathogenesis of various brain diseases, including schizophrenia, mood and anxiety disorders, autoimmune encephalomyelitis, and Alzheimer’s disease." (PMID 37076499, 2023). "After quantifying cerebral KLK8 levels in Alzheimer’s disease patients they found that its levels were similar to those described in mice." (PMID 32655372, 2020). "Notably, recent preclinical studies by Herring and the colleagues demonstrated that antibody-mediated KLK8 inhibition improves neuroplasticity and memory, reduces fear and attenuates Alzheimer's disease pathology in mice 56,57." (PMID 33754057, 2021). "This evidence suggests that KLK8 overexpression might be an important factor for the preferential prevalence of Alzheimer’s disease in females." (PMID 32655372, 2020). "Moreover, high KLK8 levels were recorded not only in Alzheimer’s disease-affected subjects but also in the healthy brains of women." (PMID 32655372, 2020). "In this context, several reports have evaluated the cerebral expression of Klk8 at both mRNA and protein levels during Alzheimer’s disease; the impact of Klk8 inhibition on Alzheimer’s disease-related pathology in mice, and primary glial cells has also been tested." (PMID 32655372, 2020). "Notably, two preclinical studies have demonstrated that inhibition of excessive cerebral KLK8 by intraventricular anti-KLK8 antibody delivery can enhance neuroplasticity, reverse molecular signatures of anxiety, and ultimately improve memory and reduce fear in Alzheimer’s disease mouse model." (PMID 37076499, 2023). "Taken together, these findings indicate that although KLK8 inhibition may become an effective strategy against diabetic myopathy, hyperkeratotic skin disease and Alzheimer's disease, it must be used with great caution due to its central nervous system side effects." (PMID 33754057, 2021). "Kallikrein-8 (KLK8) might be an early blood-biomarker of Alzheimer’s disease (AD)." (PMID 34930454, 2021). "Besides all the information referring to KLK6 and KLK8, such as their aberrant expression in Alzheimer’s disease and dementia, a recent study expanded the KLKs contribution in CNS disorders by showing that the brain of Alzheimer’s disease patients presents decreased KLK7 mRNA expression." (PMID 32655372, 2020). "In Alzheimer’s disease (AD), KLK6-8 and 10 have been suggested as AD biomarker candidates, with CSF studies indicating elevated KLK6 and KLK10 in biomarker-confirmed cases, while KLK8 remains largely unchanged and KLK7 is decreased." (PMID 41516101, 2025). "This might be due to sex-differences that emerged after the onset of Alzheimer’s disease and because estradiol, but not testosterone induces Klk8 synthesis in neurons and microglia." (PMID 32655372, 2020).
cervical cancer (6 papers, 2013 to 2025). A primary or metastatic malignant neoplasm involving the cervix. "The strongest KLK8 upregulation relative to normal tissue was observed in pancreatic adenocarcinoma (159-fold), lung squamous cell carcinoma (59-fold), colon adenocarcinoma (35-fold), cervical cancers (23-fold), and in thymoma (3-fold)." (PMID 40064965, 2025).
colon adenocarcinoma (6 papers, 2018 to 2025). "KLK6, KLK7, KLK8, and KLK10 were recently reported as potential diagnostic biomarkers for colon adenocarcinoma." (PMID 36293321, 2022). "Recent analysis of kallikrein gene family across 15 different cancers highlighted KLK6, KLK7, KLK8, and KLK10 as the excellent diagnostic biomarkers candidates for colon adenocarcinoma." (PMID 34065672, 2021). "KLK6, KLK7, KLK8 and KLK10 are considered as excellent biomarker candidates in diagnosing colon adenocarcinoma." (PMID 40156045, 2025).
colon carcinoma (6 papers, 2018 to 2024). "Similarly, the long non-coding RNA KLK8 has been implicated in influencing stem cell properties in colon cancer." (PMID 38167126, 2024). "Then, we further observed the effect of siRNA-mediated KLK8 knockdown on colon cancer cell proliferation, migration and invasion." (PMID 34552064, 2021). "Then, we performed IHC staining on 350 CRC patient samples, which confirmed that KLK8 expression was higher in the late stage of colon cancer (AJCC Cancer Staging Manual, 7th edition) (P < 0.001)." (PMID 34552064, 2021). "Three kallikreins, KLK6, KLK7, and KLK8, were found to be overexpressed in colon cancer." (PMID 36293321, 2022). "Colon cancer had four up-regulated KLKs with excellent AUC values (KLK6: 0.988, KLK7: 0.939, KLK8: 0.928, KLK10: 0.905)." (PMID 29707153, 2018).
colorectal cancer (6 papers, 2013 to 2024). A primary or metastatic malignant neoplasm that affects the colon or rectum. "However, the role of KLK8 in colorectal cancer (CRC) and the underlying mechanism remain largely unclear." (PMID 34552064, 2021). "As for KLK8, it can facilitate colorectal cancer (CRC) cell proliferation, migration and invasion in vitro." (PMID 34395235, 2021). "In colorectal cancer, KLK8 facilitated the EMT processes which could be mitigated by protease-activated receptor antagonists, suggesting that the protease activity might be the mechanism by which KLK8 exerted its tumor-promoting functions." (PMID 38273291, 2024).
pancreatic cancer (6 papers, 2021 to 2025). "In tumors, KLK8 mRNA was particularly abundant in ovarian, head and neck, esophageal, and pancreatic cancers and to a lesser extent also in melanoma." (PMID 40064965, 2025). "Our findings demonstrated that upregulation of KLK8 was related to a poor prognosis in pancreatic cancer." (PMID 34395235, 2021). "In conclusion, KLK8 overexpression exerts pro-proliferation and anti-apoptotic functions in pancreatic cancer cells via EGF signaling-dependent activation of PI3K/Akt/mTOR pathway." (PMID 34395235, 2021). "Cell proliferation and apoptosis were evaluated in KLK8-overexpressed human pancreatic cancer cell lines Mia-paca-2 and Panc-1." (PMID 34395235, 2021). "KLK8-overexpressed pancreatic cancer cells treated by LY294002 showed higher levels of apoptosis than Lv-control treated cells." (PMID 34395235, 2021). "In this study, by using two pancreatic cancer cell lines, we demonstrated for the first time that overexpression of KLK8 significantly inhibited PDAC cell apoptosis, meanwhile profoundly promoted PDAC cell proliferation." (PMID 34395235, 2021). "In this study, we explored the expression of KLK8 in the pancreatic cancer at both the mRNA and protein levels and investigated the correlation between KLK8 expression and prognosis of pancreatic cancer patients." (PMID 34395235, 2021). "Compared with normal tissues, the level of KLK8 were significantly increased in pancreatic cancer tissues (P<0.01)." (PMID 34395235, 2021). "In Lv-KLK8 treated pancreatic cancer cells, we found that LY294002 reversed the anti-apoptotic effect of KLK8 overexpression." (PMID 34395235, 2021). "The related signaling pathways of KLK8 involved in pancreatic cancer progression were analyzed by gene set enrichment analysis (GSEA) and further verified in in vitro studies." (PMID 34395235, 2021). "In contrast, the present study showed that KLK8 overexpression significantly increased cell viability of pancreatic cancer cells." (PMID 34395235, 2021). "In summary, our findings indicate that KLK8 overexpression exerts pro-proliferation and anti-apoptotic functions in pancreatic cancer cells via EGF signaling-dependent activation of PI3K/Akt/mTOR pathway." (PMID 34395235, 2021). "The present study found that lentivirus-mediated KLK8 overexpression exhibited significant pro-proliferation and anti-apoptotic effects in pancreatic cancer cells, suggesting that the active form of KLK8 is increased after KLK8 overexpression." (PMID 34395235, 2021). "In Lv-KLK8 treated pancreatic cancer cells, we found that Deguelin and Rapamycin reversed the anti-apoptotic effect of KLK8 overexpression." (PMID 34395235, 2021). "C-myc and Cyclin D1, two downstream targets of Notch signaling, were increased in pancreatic cancer cells overexpressed with KLK8." (PMID 34395235, 2021). "In this study, we identified up-regulated KLK8 expression in pancreatic cancer compared with adjacent tissues through TCGA database, which was further confirmed by using clinical samples." (PMID 34395235, 2021). "Compared with control group, the percentage of apoptosis cells was significantly reduced in KLK8 overexpressed pancreatic cancer cells." (PMID 34395235, 2021). "In the present study, GSEA analysis and western blot assay revealed that KLK8 overexpression resulted in the activation of PI3K/AKT/mTOR signaling pathway in pancreatic cancer cells." (PMID 34395235, 2021). "Moreover, KLK8-overexpressed pancreatic cancer cells treated by LY294002 showed higher levels of apoptosis than Lv-control treated cells." (PMID 34395235, 2021). "In addition, the number of cell colonies were significantly increased in both Mia-paca-2 and Panc-1 pancreatic cancer cells overexpressed with KLK8." (PMID 34395235, 2021). "We then clarified the effect of KLK8 overexpression on pancreatic cancer apoptosis." (PMID 34395235, 2021).
pancreatic cancer (continued). "Moreover, KLK8-overexpressed pancreatic cancer cells treated by Deguelin showed higher levels of apoptosis than Lv-control treated Mia-paca-2 and Panc-1 cells." (PMID 34395235, 2021). "We also investigated whether and how KLK8 affected the proliferation and apoptosis of pancreatic cancer cells." (PMID 34395235, 2021). "KLK8 overexpression also led to significant increases in phosphorylated 4EBP1 and phosphorylated S6P-p70S6K, two of the most distinctive downstream targets of mTOR, in pancreatic cancer cell lines." (PMID 34395235, 2021). "Next, we explored whether activation of PI3K-Akt-mTOR and Notch signaling pathways contributed to the pro-proliferation and anti-apoptotic functions of KLK8 in pancreatic cancer cells." (PMID 34395235, 2021). "We then determined whether elevated KLK8 expression could influence the proliferation and apoptosis of pancreatic cancer cells by using KLK8-overexpressed Mia-paca-2 and Panc-1 cell lines." (PMID 34395235, 2021). "However, KLK8-overexpressed pancreatic cancer cells treated by Deguelin showed higher levels of apoptosis than Lv-control treated Mia-paca-2 and Panc-1 cells." (PMID 34395235, 2021). "Whether these processes and the related signaling pathways contribute to the KLK8-induced pro-proliferation and anti-apoptotic effects in pancreatic cancers merits further investigation." (PMID 34395235, 2021). "However, Notch inhibitor didn’t influence the KLK8-induced effects in pancreatic cancer cells." (PMID 34395235, 2021). "Thus, we further investigated whether EGF signaling pathway contributes to KLK8-induced proliferation and anti-apoptotic effects in pancreatic cancer cells." (PMID 34395235, 2021). "KLK6, KLK7, KLK8, KLK10 and KLK11 were coexpressed and upregulated in tissues from pancreatic cancer patients compared to normal pancreas." (PMID 34439122, 2021). "However, the expression pattern and role of KLK8 in pancreatic cancer remains unknown." (PMID 34395235, 2021). "Since KLK8is typically co-expressed with KLK6 in multiple disease contexts,including in pancreatic cancer,16,29−31 initial probe development focused on an ABP selective toward KLK6over KLK8, a challenging objective in view of their common trypsin-likespecificity for Lys/Arg at P1." (PMID 36413626, 2022). "Notably, our GSEA analysis data showed that KLK8 overexpression might also lead to the activation of EMT (epithelial-mesenchymal transition), glycolysis and KRAS signaling pathway, which have been implicated in the pathogenesis and progression of pancreatic cancers." (PMID 34395235, 2021). "It was found that KLK8 mRNA levels were significantly increased in pancreatic cancer tissue samples as comparison to the adjacent non-tumor tissues (p < 0.01)." (PMID 34395235, 2021). "Furthermore, we found that high KLK8 expression predicts poorer OS and DFS in pancreatic cancer patients." (PMID 34395235, 2021). "Overexpression of KLK8 might promote proliferation and inhibit apoptosis via epidermal growth factor (EGF) signaling-dependent activation of PI3K/Akt/mTOR pathway in pancreatic cancer cells." (PMID 34395235, 2021).
psoriasis (6 papers, 2020 to 2025). An autoimmune condition characterized by red, well-delineated plaques with silvery scales that are usually on the extensor surfaces and scalp. "Enhancer homolog 2 of the Zeste gene (EZH2) is a histone H3K27 methylase, whereas EZH2 acts on kallikrein-8 (KLK8) to cause the abnormal proliferation of keratinocytes in psoriasis." (PMID 37762693, 2023). "Experiments with mice showed an increase in KLK6, KLK7, and KLK8 mRNA levels when Psoriasis-like lesions were induced." (PMID 35356049, 2021). "Results from immunohistochemical staining showed that the expression of KLK8 was increased greatly in epidermis of psoriasis lesional skin, which is consistent with the change of EZH2." (PMID 33011750, 2020). "Then we detected the expression of KLK8 from skin tissue sample of psoriasis patients and healthy controls." (PMID 33011750, 2020). "In conclusion, our study showed upregulated EZH2 in psoriatic epidermis, which might catalyze trimethylation of H3K27, inducing the expression of KLK8 and further promotes keratinocyte proliferation in psoriasis." (PMID 33011750, 2020). "KLK8 is also involved in the formation of microabscess in imiquimod-induced psoriasis-like mice." (PMID 33011750, 2020). "In this report, we showed that EZH2 promoted the proliferation of keratinocyte through KLK8, and inhibition of EZH2 had a therapeutic effect on psoriasis in imiquimod-induced psoriasis-like mouse model." (PMID 33011750, 2020). "Moreover, KLK8 could also be stimulated by psoriasis-related mixed cytokines." (PMID 33011750, 2020). "However, the same experience conducted in KLK8 knockout mice did not result in KLK6 and KLK7 mRNA upregulation, suggesting a determinant role of KLK8 in proteolytic cascade in Psoriasis." (PMID 35356049, 2021).